MFN2 (mitofusin 2)
Diseases named in the same sentence as MFN2 in open-access papers (continued):
Sharing a sentence is not in itself a finding about the gene and the disease.
MERRF syndrome (2 papers, 2020 to 2025). A rare mitochondrial oxidative phosphorylation disorder characterized by myoclonic seizures, ataxia, generalized epilepsy, muscle weakness and ragged red fibers in the muscle biopsy. "Genetic investigations have identified familial cases associated with mutations in mitofusin 2 (MFN2) and hormone-sensitive lipase (LIPE) genes, as well as mitochondrial DNA variants linked to myoclonic epilepsy with ragged red fibers syndrome (MERRF syndrome)." (PMID 40746792, 2025). "Intriguingly, multiple lipomatosis, as previously observed in myoclonic epilepsy and ragged-red fibres (MERRF) syndrome but no other forms of primary mtDNA mutations, has been identified in several families of MFN2 mutations." (PMID 32858900, 2020).
microcephaly (2 papers, 2020 to 2024). A congenital or acquired developmental disorder in which the circumference of the head is smaller than normal for the person's age and sex. "In previous reports, MFN2-knockout cells displayed mitochondrial spheres or ovals of widely different sizes, including some with a diameter several-fold larger than wild type mitochondrial tubules, similar to the mitochondrial phenotype of infants with microcephaly." (PMID 33424801, 2020).
Mitochondrial myopathy (2 papers, 2020 to 2025). "Similar cristae disorganization was reported in a mitochondrial myopathy and human patients carrying Mfn2 mutations." (PMID 31947766, 2020).
osteoarthritis (2 papers, 2023 to 2024). A noninflammatory degenerative joint disease occurring chiefly in older persons, characterized by degeneration of the articular cartilage, hypertrophy of bone at the margins and changes in the synovial membrane. "On the contrary, in the situation of aging, previous results indicate that MFN2 expression was elevated in both human and rat chondrocytes during aging and osteoarthritis, and overexpression of MFN2 exacerbated inflammation and osteoarthritis progress." (PMID 38566081, 2024). "Mitofusin 2 (Mfn2) is considered to be a significant regulator of cellular metabolism and inflammation, and the downregulation of Mfn2 can reduce inflammation in osteoarthritis." (PMID 37723417, 2023).
Pes cavus (2 papers, 2016 to 2021). An increase in height of the medial longitudinal arch of the foot that does not flatten on weight bearing (i.e., a distinctly hollow form of the sole of the foot when it is bearing weight). "His mother harboring the same MFN2 variants was subclinical with pes cavus as the only clinical presentation." (PMID 35153971, 2021).
prediabetes (2 papers, 2017 to 2020). "A significant increase in MFN2 expression was observed in subjects with prediabetes relative to the controls (p < 0.05)." (PMID 29326655, 2017). "In subjects with prediabetes, MFN2 (r = 0.558; p < 0.01), PINK1 (r = 0.534; p < 0.01), NIX (r = 0.637; p < 0.01) and LC3-II (r = 0.667; p < 0.01) mRNA expression was significantly and positively correlated with the HbA1C levels." (PMID 29326655, 2017). "In subjects with prediabetes, MFN2 expression (r = 0.438; p = 0.05) showed a positive correlation with HbA1C levels." (PMID 29326655, 2017). "It has also been demonstrated that the expression levels of Mitofusin-2 (MFN2), NIX, PINK1, and PARKIN were augmented in prediabetes in comparison with healthy ones." (PMID 33041786, 2020). "Our study is the first report to demonstrate that MFN2, NIX, PINK1, and PARKIN expression was increased in subjects with prediabetes as compared to the healthy controls." (PMID 29326655, 2017). "However, mRNA expression of MFN2, PARKIN, and LC3-II were found to be significantly decreased in subjects with NDT2DM and ADT2DM as compared to the controls and subjects with prediabetes (p < 0.05)." (PMID 29326655, 2017). "A significant increase in MFN2 and LC3-II gene expression was observed in subjects with prediabetes vs. controls (p < 0.05), while, PARKIN showed a non-significant increase in the prediabetic group." (PMID 29326655, 2017).
prion disease (2 papers, 2019 to 2024). A transmissible disease that is caused by a protein that is able to induce abnormal folding of normal cellular proteins, leading to characteristic spongiform brain changes, which are associated with neuronal loss without an inflammatory response. "Mitochondrial dynamics are disrupted during prion disease, where expression levels of a key protein involved in mitochondrial fission, dynamin-related protein 1 (Drp1), and a key protein involved in mitochondrial fusion, mitofusion 2 (MFN2), are altered." (PMID 38394123, 2024). "To search for other mitochondrial fusion proteins involved in mitochondrial network fragmentation and mitochondrial dysfunction in prion diseases, in this study we investigated the expression of mitochondrial fusion-regulating proteins, OPA1, MFN1, and MFN2." (PMID 31551424, 2019).
tauopathy (2 papers, 2022 to 2025). Neurodegenerative disorders involving deposition of abnormal tau protein isoforms (tau proteins) in neurons and glial cells in the brain. "This persistence of MFN2(+) neurons in areas of high tauopathy potentially reflects a neuronal protective response to injury as has been studied in animal and in vitro models of neuronal degradation." (PMID 36333818, 2022). "In this study, we observed an upregulation of the mitochondrial fission protein DRP1 in the SH‐SY5Y tauopathy model, while the levels of fusion proteins MFN1, MFN2, and OPA1 remained unchanged." (PMID 40344412, 2025).
tuberculosis (2 papers, 2022). A chronic, recurrent infection caused by the bacterium Mycobacterium tuberculosis. "In this sense, MFN2 has been shown to be implicated in controlling the ability of Mtb to survive and replicate within macrophages ex vivo and in a mouse infection model, consistent with GWAS that identified human SNPs in MFN2 associated with tuberculosis susceptibility in a Han Chinese population." (PMID 36076909, 2022). "Transcriptional profiling in human PBMCs from active tuberculosis patients and healthy controls determined that a mitochondrial outer membrane protein, MFN2 expression was significantly upregulated in TB patients compared to healthy controls." (PMID 35237260, 2022).
acute myeloid leukemia (1 paper, 2022). Acute myeloid leukemia (AML) is a group of neoplasms arising from precursor cells committed to the myeloid cell-line differentiation. "Consistently, time-dependent exposure to doxorubicin, and increased levels of MFN1, MFN2, and OXPHOS in response to doxorubicin, are usually associated with fusion-driven chemoresistance in Jurkat leukemia cells, acute myeloid leukemia (AML), and ovarian cancers." (PMID 36359776, 2022).
alcoholic liver diseases (1 paper, 2023). A disorder caused by damage to the liver parenchyma due to alcohol consumption. "PGC-1α was reported as an upstream mediator of MFN2 in alcoholic liver disease and liver ischaemia-reperfusion injury." (PMID 38012555, 2023).
Anisocoria (1 paper, 2016). Anisocoria, or unequal pupil size, may represent a benign physiologic variant or a manifestation of disease. "Furthermore, anisocoria [PMP22, MPZ, MFN2, SH3TC2; FYVE, RhoGEF, and PH domain‐containing protein 4 (FGD4) gene], miosis (PMP22, MPZ) and mydriasis (MPZ) have been described previously." (PMID 27088055, 2016).
aortic stenosis (1 paper, 2020). Aortic valve stenosis is a aortic valve disease caused by the incomplete opening of the aortic valve. "MFN2 expression was unchanged in rat pressure overload (PO)-induced HF model and in LV subepicardial biopsies from patients with HFpEF and HFrEF related to ischemic heart disease (IHD) or severe aortic stenosis (AS) compared to normal." (PMID 33172082, 2020).
asthenozoospermia (1 paper, 2022). "This suggests that the specific regulation of Mfn2 expression levels in the sperm of patients might help to alleviate asthenozoospermia and the reduction in progressive sperm motility caused by mitochondrial dysfunction." (PMID 35725948, 2022). "Additionally, although current research related to Mfn2 and reproduction has provided us with a wealth of therapeutic ideas for alleviating or treating early embryo loss and death, PCOS, asthenospermia, and other common human reproductive disorders." (PMID 35725948, 2022). "In asthenozoospermic patient, the sperm exhibits mitochondrial dysfunction with a markedly reduced expression level of Mfn2; this may be the trigger for the reduced sperm motility seen in asthenozoospermia and may arise by the regulation of mitochondrial dysfunction." (PMID 35725948, 2022).
bladder tumor (1 paper, 2021). "Samples of the main bladder tumor and healthy-looking bladder wall from patients classified as NMIBC were tested for Mfn2 and ClpP." (PMID 34441434, 2021).
breast tumors (1 paper, 2021). "It has been also reported that reduced MFN2 levels in breast tumors are associated with poorer outcomes, and cell lines with silenced MFN2 display increased viability and aggressiveness, which seems to be mediated by mTORC2/AKT." (PMID 34073868, 2021).
carotid atherosclerosis (1 paper, 2020). A thickening and loss of elasticity of the walls of carotid arteries that occur with formation of atherosclerotic plaques. "In addition, in apolipoprotein E (ApoE)-deficient mice, the progression of carotid atherosclerosis is accompanied by a decrease in MFN2 levels, and overexpression of MFN2 inhibits oxLDL-induced VSMC proliferation during atherogenesis." (PMID 33240899, 2020).
Cerebellar atrophy (1 paper, 2021). Cerebellar atrophy is defined as a cerebellum with initially normal structures, in a posterior fossa with normal size, which displays enlarged fissures (interfolial spaces) in comparison to the foliae secondary to loss of tissue. "However, there was no statistically significant cerebellar atrophy in the other genotypes (PMP22 duplication, MFN2, or GJB1 mutation)." (PMID 34768465, 2021).
cerebellar degeneration (1 paper, 2010). Degeneration of the cerebellum. "The fundamental importance of mitochondrial remodelling in mammalian pathophysiology has been underlined by in utero lethality and cerebellar degeneration in mice with homozygous mutations in Dnm1l itself, as well as Mfn1, Mfn2, or Opa1." (PMID 20585624, 2010).
cholestasis (1 paper, 2013). Impairment of the bile flow caused by obstruction within the liver, or outside the liver in the bile duct system. "Therapeutic approaches that target Mfn2 may have protective effects against hepatotoxic of bile acids during cholestasis." (PMID 23755235, 2013).
Cirrhosis (1 paper, 2018). A chronic disorder of the liver in which liver tissue becomes scarred and is partially replaced by regenerative nodules and fibrotic tissue resulting in loss of liver function. "Whether MFN2 is causative to cirrhosis requires further research." (PMID 30498519, 2018). "Patients with low expression of MFN2 had significantly higher rates of cirrhosis than those with high expression of MFN2 (P = 0.049)." (PMID 30498519, 2018).
colon adenoma (1 paper, 2019). An adenoma that arises from the colon. "In accordance to this, ApcMin/+ mice, which develop spontaneous intestinal and colon adenomas, showed diminished MFN1, MFN2 and PGC-1α protein expression in advance to the decrease of muscle mitochondrial content." (PMID 31466311, 2019).
congenital cataracts (1 paper, 2018). "Without the Mfn2 gene at the head surface ectoderm, mice are born with congenital cataracts and microphthalmia." (PMID 29367651, 2018).
COVID-19 (1 paper, 2024). A disease caused by infection with severe acute respiratory syndrome coronavirus 2. "Among the mitobiomarkers associated with the pulmonary version of COVID-19 are PTEN-induced kinase 1 (PINK1), dynamin-1-like protein (DNM1L) and mitofusin-2, which supports the relevance of oxidative stress and aberrations in mitochondrial motility (Chapter 9) in COVID-19 pathogenesis." (PMID 38974521, 2024). "Interestingly, only patients with mild COVID-19 (but not those with severe cases) had a lower abundance of various mitochondrial proteins, including Opa1, Mfn2 and SDHB (succinate dehydrogenase subunit)." (PMID 38974521, 2024).
cutaneous melanoma (1 paper, 2024). A primary melanoma arising from atypical melanocytes in the skin. "In cutaneous melanoma, high mitofusin 2 levels are associated with the degree of skin penetration and significantly correlate with lymph node involvement and metastasis." (PMID 38195762, 2024).
deficiencies (1 paper, 2018). "Deletion of Mfn1 and Mfn2 in skeletal muscle results in reduction of mtDNA and respiratory deficiencies." (PMID 30333037, 2018).
dengue virus infection (1 paper, 2022). "After dengue virus infection, Mfn2 are cleaved by dengue virus protease NS2B3, and the Mfn2 keeps MMP to inhibit cell death from dengue virus infection." (PMID 35958608, 2022).
diabetic neuropathy (1 paper, 2021). A chronic, pathological complication associated with diabetes mellitus, where nerve damages are incurred due to diabetic microvascular injury involving small blood vessels that supply these nerves, resulting in peripheral and/or autonomic nerve dysfunction. "Although a peripheral neuropathy noted in the D414V patient was initially attributed to a diabetic neuropathy, it is worth considering the contribution of MFN2 dysfunction to this phenotype." (PMID 38274408, 2021).
emerinopathy (1 paper, 2022). "Therefore, MFN2 function and interplay between fusion and fission in cardiac emerinopathy could be an interesting topic for further research." (PMID 36106556, 2022).
emphysema (1 paper, 2023). "Reduced expression of MFN1, MFN2 and OPA1 were also seen in alveolar epithelial cells in emphysema/COPD patients." (PMID 38110986, 2023).
Endometrial Cyst (1 paper, 2023). It is caused by endometriosis, and formed when a tiny patch of endometrial tissue (the mucous membrane that makes up the inner layer of the uterine wall) bleeds, sloughs off, becomes transplanted, and grows and enlarges inside the ovaries. "Increased oxidative stress and ROS accumulation have been found in serum, peritoneal fluid, and ectopic endometrial cysts in patients with endometriosis, which can reduce the expression of MFN1, MFN2, and OPA1, compatible with our result." (PMID 37393390, 2023).
endometriosis (1 paper, 2023). The growth of functional endometrial tissue in anatomic sites outside the uterine body. "Here, we demonstrated a decline in mRNA and protein expression levels of DRP1, OPA1, MFN1, and MFN2 in ectopic ESCs and tissue and a decrease in mitochondrial number in endometriosis." (PMID 37393390, 2023). "We detected elevated DRP1, OPA1, MFN2, and LCLAT1 in eutopic ESCs in patients with endometriosis than in controlled group." (PMID 37393390, 2023).
fibrosis (1 paper, 2022). the formation of excess fibrous connective tissue in an organ or tissue in a reparative or reactive process. "Conversely, a research group that analyzed melatonin properties in NAFLD‐derived fibrosis reported a raise in autophagosomes, mitofusin 2 (Mfn2), and a decrease in cytoplasmic SQSTM1/p62 levels." (PMID 35404472, 2022).
focal segmental glomerulosclerosis (1 paper, 2023). A renal disorder characterized by sclerotic lesions in the glomeruli. "Our previous study showed that Mfn2 deficiency participates in podocyte injury in a focal segmental glomerulosclerosis (FSGS) animal model by inhibiting Pink1/Parkin-associated mitophagy." (PMID 36998021, 2023).
gestational diabetes (1 paper, 2015). Carbohydrate intolerance first diagnosed during pregnancy. "Moreover, mitofusin-2 expression was also reduced in the gestational diabetes offspring fed HFS diets." (PMID 26512955, 2015).
HCMV infection (1 paper, 2022). "The results showed that the expression of genes regulating mitochondrial fusion (MFN1 and MFN2) was decreased after HCMV infection, while the expression of genes regulating mitochondrial division (Drp1 and FIS1) was upregulated." (PMID 35359726, 2022).
hepatitis B (1 paper, 2018). "This study was designed to explore the expression level of MFN2 in the cancer tissues of patients with hepatitis B-related HCC, analyze the relationship between the expression level of MFN2 and clinicopathological features, and investigate its role in the regulation of hepatitis B-related HCC." (PMID 30498519, 2018).
HIV-1 infection (1 paper, 2025). The type species of lentivirus and the etiologic agent of acquired immunodeficiency syndrome (AIDS). "Furthermore, human immunodeficiency virus type 1 (HIV-1) infection increased Mfn1 and Mfn2 protein levels, protecting against MMP depolarization, which contributes to inhibiting apoptosis and supporting viral proliferation." (PMID 40284870, 2025).
homocystinuria (1 paper, 2016). An autosomal recessive inherited metabolic disorder caused by mutations in the CBS, MTHFR, MTR, and MTRR genes. "The up-regulation at protein level of three MAM-associated proteins (Grp75, σ-1R and Mfn2) observed in homocystinuria patients ́ cells may indicate an altered ER-mitochondrial communication suggesting an aberrant calcium homeostasis in this disease." (PMID 26959487, 2016). "Since MAM-associated proteins play an important role in calcium shuttling, we have analysed the expression of Grp75, σ-1R and Mfn2 in fibroblasts from patients with homocystinuria by immunoblotting." (PMID 26959487, 2016).
Hypercholesterolemia (1 paper, 2022). An increased concentration of cholesterol in the blood.
hyperhomocysteinemia (1 paper, 2023). A serious metabolic condition caused by mutations in the MTHFR gene, medications, or nutritional deficiency. "In the hyperhomocysteinemia rat model, the mitophagy‐related proteins FUN14 domain containing 1 and LC3B and the mitochondrial fusion proteins Mfn1 and Mfn2 are down‐regulated, whereas expression of the mitochondrial fission protein Drp1 is up‐regulated." (PMID 37208948, 2023).
Hypertonia (1 paper, 2018). A condition in which there is increased muscle tone so that arms or legs, for example, are stiff and difficult to move. "By using co-immunoprecipitation analyses, we found that endogenous Trak1 specifically interacted with Mfn1 and Mfn2 but not with Drp1 and that the ability of Trak1 to interact with mitofusins was not affected by hypertonia-associated mutation." (PMID 28924745, 2018).
hypertrophic cardiomyopathy (1 paper, 2023). A condition in which the myocardium is hypertrophied without an obvious cause. "(B) Sequencing pherogram from a hypertrophic cardiomyopathy subject showing heterozygous MFN2 R400Q mutation (arrow)." (PMID 37910431, 2023).
hyperuricemia (1 paper, 2025). An abnormally high level of uric acid. "To investigate the mechanisms of hyperuricemia-related cardiovascular diseases, we examined the expression of mitochondrial fission 1 protein (FIS1), as well as mitofusin 1 (MFN1) and mitofusin 2 (MFN2), which are key regulators of mitochondrial fusion." (PMID 40361044, 2025).
hypogonadism (1 paper, 2021). A disorder characterized by decreased function of the gonads. "Moreover, hypogonadism was found to affect mitofusin (Mfn1) and mitofusin (Mfn2) in the Leydig cells by reducing the transcription of Drp1, as well as Mfn1 and Mfn2, without changing protein optic atrophy 1 (Opa1) levels." (PMID 34440620, 2021).
intervertebral disc degeneration (1 paper, 2023). "This study is the first time to reveal the relationship between MFN2 and immune cell infiltration during intervertebral disc degeneration." (PMID 36968589, 2023).
lentivirus infection (1 paper, 2021). Virus diseases caused by the Lentivirus genus. "Before lentivirus infection was performed in hESCs, knockdown efficiency of the MFN2-shRNA was examined in HEK cells and MFN2 knockdown efficiency was compared between MFN2 RNAi #1, MFN2 RNAi #2, and Luc RNAi using qRT-PCR." (PMID 34602978, 2021).